TFF1 (trefoil factor 1)
Diseases named in the same sentence as TFF1 in open-access papers (continued):
Sharing a sentence is not in itself a finding about the gene and the disease.
retinoblastoma (8 papers, 2016 to 2025). A malignant tumor that originates in the nuclear layer of the retina. "Another gene whose promoter’s hypermethylation is a sign of retinoblastoma is the Trefoil Factor Family gene (TFF1), a gene that encodes a protein that regulates the epithelial integrity of the retina cells." (PMID 41150792, 2025). "Moreover, genome-wide methylation profiling of aqueous humor cfDNA has defined robust subtypes of retinoblastoma linked to clinical outcomes, identifying differentially methylated genes (e.g., TFF1, BCHE, PCDHB2, ADAM33) that correlate with aggressive disease and chemoresistance." (PMID 41150792, 2025). "TFF1, a recently characterized marker of metastatic potential observed in subtype 2 retinoblastoma, was also heterogeneously expressed in PD areas only." (PMID 40898088, 2025). "The proposed surrogate marker for subtype 2 retinoblastoma, TFF1, was hypomethylated and strongly expressed in clusters B and C." (PMID 39079981, 2024). "Next, we investigated GIPR’s expression levels in retinoblastoma primary tumor tissue and correlated them with TFF1 expression." (PMID 38730608, 2024). "Our group demonstrated that TFF1 acts as a tumor suppressor in the progression of retinoblastoma by reducing RB cell viability, growth, and proliferation and increasing apoptosis in vitro as well as inhibiting tumor growth in vivo." (PMID 38730608, 2024). "By evaluating TFF1 staining in tumor sections post-enucleation, we and others already suggested TFF1 as a potential biomarker for a specific subset of retinoblastomas." (PMID 37835522, 2023). "A promising candidate in this context is the secreted trefoil family factor peptide 1 (TFF1), recently discovered as a promising new biomarker in patients with a more advanced subtype of retinoblastoma." (PMID 37835522, 2023). "The TFF1 expression status of 15 retinoblastoma AH samples was investigated by ELISA and Western blot analyses." (PMID 35158945, 2022). "We therefore investigated for the first time aqueous humor samples of retinoblastoma patients in order to test for the availably and expression status of TFF1 as well as to compare it with the original tumor and established corresponding primary cell cultures." (PMID 35158945, 2022). "We assessed TFF1 protein expression by immunohistochemistry, in 55 of the tumors from our initial series of 102 classified retinoblastomas (18 subtype 1 and 37 subtype 2 tumors)." (PMID 34552068, 2021). "TFF1 is a promising candidate as it is expressed in a more advanced subtype of retinoblastoma." (PMID 35158945, 2022). "In a very recent study, we discovered TFF1 expression in a specific subgroup of retinoblastoma (RB) tumors with advanced stages, and found this soluble peptide to be secreted into the aqueous humor of RB patients." (PMID 37835522, 2023). "One of the two extraocular retinoblastomas that we analyzed was unexpectedly a cluster A, subtype 1 retinoblastoma without elevated TFF1 expression." (PMID 39079981, 2024). "Moreover, we previously discovered that TFF1 levels correlate with a higher clinical RB tumor-node-metastasis (TNM) stage, and, recently, TFF1 was described as a biomarker in retinoblastoma patients with a more advanced subtype and poor prognosis." (PMID 38730608, 2024).
inflammatory bowel disease (7 papers, 2013 to 2025). A spectrum of small and large bowel inflammatory diseases of unknown etiology. "Given TFF1 long known association with inflammatory bowel disease, a condition seen in overlap with AS, and the large prevalence of colitis in AS, our newly identified DEPs may be useful AS biomarkers." (PMID 37041650, 2023). "MUC5AC and TFF1 expression in goblet cells is common in inflammatory bowel disease and other inflammatory conditions of the colon, suggesting that these changes represent a nonspecific repair function of the colon cells to compensate for damage to barrier function." (PMID 24829572, 2014). "MUC5AC and TFF1 expression in goblet cells is common in inflammatory bowel disease and other inflammatory conditions of the colon, suggesting that these changes may represent a nonspecific repair function of the colon cells to compensate for damage to barrier function." (PMID 23691335, 2013). "However, some research has shown a connection between inflammatory bowel diseases, such as chronic pancreatitis, Barrett’s esophagus, peptic ulcers, and inflammatory bowel disease, and increased TFF1 production through mechanisms that are not yet fully understood." (PMID 41471915, 2025).
asthma (6 papers, 2017 to 2024). "In a murine asthma model, IL-13 seems to induce TFF1 expression in Clara cells (Clara cell metaplasia), which are able to trans-differentiate into goblet cells." (PMID 34066339, 2021). "Of special note, TFF1 in particular is ectopically expressed in various chronic inflammatory conditions, even in murine models of encephalitis and asthma, and in the murine spleen after Toxoplasma gondii infection." (PMID 32630599, 2020). "Additionally, expression of ependymin-related protein 1 (Epdr1; previously termed Merp2) was monitored, because it was downregulated in a murine asthma model; whereas Tff1 was upregulated in this model." (PMID 31963721, 2020). "This assumption is supported by the observation that TFF1 is ectopically expressed during various chronic inflammatory conditions in humans, as well as in animal models of pancreatitis, asthma, and encephalitis, and in the murine spleen after T. gondii infection." (PMID 32630599, 2020). "This might also explain, why in mammals TFF1 is ectopically expressed during various inflammatory conditions, such as duodenal ulcers, Crohn’s disease, pancreatitis, asthma, encephalitis, and in the murine spleen after Toxoplasma gondii infection." (PMID 31801293, 2019). "Furthermore, a role for Tff1 as a scavenger for ROS/RNS could also be the reason why Tff1 is ectopically expressed during various inflammatory conditions in mice, such as encephalitis, asthma, pancreatitis, and in the murine spleen after Toxoplasma gondii infection." (PMID 31963721, 2020).
gastric adenocarcinoma (6 papers, 2013 to 2024). "In human, TFF1 expression is downregulated in approximately two-thirds of gastric adenocarcinoma due to deletion, loss of heterozygosity, hypermethylation, or transcription regulation." (PMID 25980439, 2015). "Our data demonstrated that H. pylori infection significantly enhances cell proliferation and the incidence of invasive gastric adenocarcinoma in the Tff1-KO mice." (PMID 25980439, 2015). "However, only one-third of the H. pylori infected Tff1-KO mice developed invasive gastric adenocarcinoma." (PMID 25980439, 2015). "However, studies have shown that not all gastric adenocarcinomas produce TFF1 and that various other tumor entities can express TFF1." (PMID 39410561, 2024). "In order to analyze the effect of TFF1 restoration in a model system that does not express it, we used a TFF1 inducible hyper-expressing clone (AGS-AC1) derived from the gastric adenocarcinoma cell line AGS." (PMID 29997345, 2018). "Adherence of H. pylori to gastric adenocarcinoma cells, AGS AC1 cells, induced to hyper-express TFF1 was enhanced compared to noninduced cells." (PMID 24236136, 2013).
metastatic disease (6 papers, 2018 to 2023). "Although not statistically significant, most GCs cases with the presence of metastatic disease (88.9%) displayed a reduced expression of TFF1 (p = 0.186)." (PMID 34679875, 2021).
pancreatitis (6 papers, 2018 to 2024). Inflammation of the pancreas. "Il33 is expressed during pancreatitis by a small subset (4%) of TFF1/ANXA10+Kras-mutant Gastric module-expressing epithelial cells and is predicted to initiate signaling to Tregs and ILCs (Module T8) by binding with its cognate receptor Il1rl1 and co-receptor Il1rap." (PMID 37167403, 2023). "Although there has been limited research into its role in the intestinal tract, TFF1 is observed to increase at sites of intestinal inflammation, such as in patients with active IBD, and in some non-intestinal inflammatory conditions, such as pancreatitis." (PMID 39596084, 2024).
prostate carcinoma (6 papers, 2004 to 2025). A carcinoma that arises from epithelial cells of the prostate gland. "Previous reports indicate that patients with advanced prostate cancer have significantly higher plasma concentrations of TFF1." (PMID 31303963, 2019). "We have previously reported that TFF1 repressed CDH1 expression in prostate carcinoma cells to promote cell invasion." (PMID 25266665, 2014). "For instance, while ligand-independent activation of PPAR-δ exerted tumor suppressive functions in prostate cancer by repressing trefoil factor 1 (TFF1), PPARD expression has been correlated with cancer progression, angiogenesis, and metastasis in several cancers." (PMID 41148824, 2025). "Interestingly, the forced expression of TFF1 in DU145 prostate cancer cells led to increased expression of Snail as well as decreased expression of E-cadherin." (PMID 23675462, 2013).
colitis (5 papers, 2015 to 2024). Inflammation of the colon. "For example, gavage of colitis mice with TFF1-overexpressing Lactococcus lactis achieved much greater efficacy than oral or rectal administration of pure recombinant TFF1." (PMID 35039476, 2022). "Similar results were reported in a rat model of acid induced colitis, in which an elevated TFF1 expression in the distal colon was found during the acute phase of the disease." (PMID 26390128, 2015). "As illustrated in the heatmap, there were three genes that were significantly downregulated by colitis induction (TNBS + Veh) and restored after disease mice were treated with I3C (TNBS + I3C), which included one mucin protein (Muc2) and two goblet cell markers (Tff1 and Tff3)." (PMID 38397081, 2024).
colon carcinoma (5 papers, 2014 to 2024). "In the current study, we investigated the role of TFF1 activity in L1-mediated colon cancer development and progression." (PMID 36139637, 2022). "Among the markedly increased genes in SSA/Ps that have also been reported to be increased in colon cancer were REG4, AQP5, MUC2, TFF1, KLK10." (PMID 24533081, 2014).
encephalitis (5 papers, 2017 to 2021). An acute inflammatory process affecting the brain parenchyma. "Furthermore, TFF1 (but not TFF2 or TFF3) is up-regulated in two murine encephalitis models, probably in neurons (e.g., in internal granular layer of the cerebellum)." (PMID 34066339, 2021).
colorectal cancer (4 papers, 2020 to 2025). A primary or metastatic malignant neoplasm that affects the colon or rectum. "TFF3, TFF1, SELE, AHCY, LCN2, CEACAM5, and RETN are consistently upregulated across a variety of datasets and analyzes, which supports their crucial roles in the underlying mechanisms of colorectal cancer progression." (PMID 39839775, 2024). "TFF1 is mainly expressed in digestive tract epithelial cells, and is mainly involved in the protection of the gastrointestinal tract via the repair of epithelial cells; it is highly expressed in gastric and colorectal cancer." (PMID 37193028, 2023). "Further comparison of gene expression differences between right-sided and left-sided colorectal cancer tumor cells revealed that genes such as MTRNR2L8, CHRNA7, TFF1, and LYZ were more highly expressed in right-sided colorectal cancer." (PMID 41174721, 2025). "Protein quantitative trait loci analyze studies provided further evidence for the involvement of TFF1, CEACAM5, and SELE in colorectal cancer, with possible connections to the PI3K/Akt and MAPK signaling pathways." (PMID 39839775, 2024). "Seven proteins namely TFF3, LCN2, CEACAM5, TFF1, SELE, RETN, and AHCY proteins of both phases were found to be upregulated in colorectal cancer in human protein atlas database, also were significant in our UK Biobank dataset and had an essential function in CRC." (PMID 39839775, 2024). "Seven proteins, TFF3, LCN2, CEACAM5, TFF1, SELE, RETN, and AHCY were found to be upregulated in other databases and also in our UK Biobank where TFF3 and LCN2 were found to be the most significant proteins and were highly expressed in colorectal cancer." (PMID 39839775, 2024).
endometrial cancer (4 papers, 2013 to 2024). Primary or metastatic malignant neoplasm involving the endometrium (mucous membrane that lines the endometrial cavity). "PGR (Progesterone receptor), FOXA1 (Forkhead box protein A1), XBP1 (X-box binding protein 1), and TFF1 (Trefoil factor 1) were reported to involve in the estrogen signal in endometrial cancer." (PMID 33324448, 2020). "Extracts of Glycyrrhiza species and spent hops induced estrogen responsive alkaline phosphatase activity in endometrial cancer cells, estrogen responsive element (ERE)-luciferase in MCF-7 cells, and Tff1 mRNA in T47D cells." (PMID 23874474, 2013).
gastric adenoma (4 papers, 2014 to 2025). A neoplastic polyp that arises from the stomach. "Similarly, TFF1 knockout mice have been shown to develop both gastric adenomas and carcinomas." (PMID 24720760, 2014).
hepatocellular carcinoma (4 papers, 2021 to 2025). A malignant tumor that arises from hepatocytes. "We previously reported that loss of TFF1 was associated with Wnt/ Notch pathways in vivo; Notch signaling pathway in the liver was downregulated in TFF1KO mice after CDE diet and β-catenin was activated in hepatocellular carcinoma found in TFF1KO mice." (PMID 40940735, 2025).
lung carcinoma (4 papers, 2012 to 2024). "Using SiRNA interference technology, we successfully knocked down TFF1 in murine-derived lung cancer cells (LEWIS) and human lung cancer cells (TE1)." (PMID 39539551, 2024). "Knockdown of TFF1 inhibited the proliferation of lung cancer cells, reduced colony formation efficiency, and increased apoptosis rates." (PMID 39539551, 2024). "The levels (pg/ml) of secreted TFF1 proteins in the serum of lung cancer patients (squamous cell lung carcinoma, 239.4±78.3; adenocarcinoma, 210.3±42.2; SCLC, 222.2±95.1) are slightly higher when compared with the levels in healthy individuals (151.8±56.3)." (PMID 22246423, 2012). "Two early reports described that TFF1 levels in serum are increased in patients with lung cancer and positive expression of TFF1 indicates worse prognosis of lung cancer." (PMID 22246423, 2012). "Moreover, flow cytometry analysis revealed a marked increase in apoptosis rates in TFF1 knockdown cells compared to controls, further confirming the essential role of TFF1 in maintaining the malignant phenotype of lung cancer cells." (PMID 39539551, 2024). "Importantly, experimental validation demonstrated that silencing the CR TFF1 inhibited tumor growth and reduced the malignant behavior of LUAD cells in vitro and in vivo, indicating that TFF1 may be a promising therapeutic target for lung cancer treatment." (PMID 39539551, 2024). "In this study, we investigated the protein and mRNA levels of TFF1, TFF2 and TFF3 in tissues of lung cancer patients and healthy individuals, and lung cancer cell lines and normal cell lines." (PMID 22246423, 2012). "In our experiments, it was found that TFF1 and TFF2 levels (for the mean values of all detected patients) in the serum of lung cancer patients were slightly higher than in healthy individuals." (PMID 22246423, 2012). "It was found that TFF1 and TFF2 have similar or slightly higher levels in these three subtypes of lung cancer compared to healthy individuals, while TFF3 levels were significantly higher in the examined lung cancer cases compared to healthy individuals." (PMID 22246423, 2012). "Although we are not entirely clear on how S100A7 regulates DNp63, TFF1 and napsin A expression in lung cancer cells, our findings provide a novel pathway of lung cancer phenotypic plasticity during tumor progression." (PMID 28177901, 2017). "However, the levels (the mean OD values of the respective bands) of TFF1 and TFF2 in lung cancer patient were similar to those in healthy individuals." (PMID 22246423, 2012). "However, the roles of TFF1, TFF2 and TFF3 are still unclear in the prediction and prognosis of lung cancer." (PMID 22246423, 2012). "It was found that TFF1 and TFF2 levels were similar or slightly higher in these three subtypes of lung cancer compared to those in healthy individuals, while TFF3 levels were significantly higher in the detected lung cancer cases compared to healthy individuals." (PMID 22246423, 2012). "Levels of TFF1 and TFF2 transcripts in lung cancer cell lines (LK-2, A549 and MS-1) were slightly higher or not significantly different from those in the normal cell line NuLi-1." (PMID 22246423, 2012). "Levels of TFF1 and TFF2 transcripts in lung cancer tissues were slightly higher or not significantly different from those in normal tissues from the 60 healthy individuals." (PMID 22246423, 2012). "Immunoblot analyses of TFF1, TFF2 and TFF3 indicated that lung cancer tissues and lung cancer cell lines have higher expression levels of TFF3 protein, but not of TFF1 and TFF2 proteins, compared to tissues from healthy individuals or from normal cell line." (PMID 22246423, 2012). "Levels of TFF1 and TFF2 in lung cancer tissues were slightly higher or not significantly different from those in normal tissues from the 60 healthy individuals." (PMID 22246423, 2012).
lung carcinoma (continued). "Levels of TFF1 and TFF2 in lung cancer cell lines (LK-2, A549 and MS-1) were slightly higher or not significantly different from those in the normal cell line NuLi-1." (PMID 22246423, 2012). "Quantitative RT-PCR analysis indicated higher levels of TFF3, but not TFF1 and TFF2, transcripts in lung cancer tissues or cell lines." (PMID 22246423, 2012). "Immunoblot analyses of TFF1, TFF2 and TFF3 indicated that lung cancer tissues and lung cancer cell lines have a higher expression of the TFF3 protein, but not of TFF1 or TFF2 proteins, compared to tissues from healthy individuals or from the normal cell line." (PMID 22246423, 2012). "Quantitative RT-PCR analysis of TFF1, TFF2 and TFF3 transcripts in tissues and cell lines indicated higher levels of TFF3, but not of TFF1 and TFF2 transcripts in lung cancer tissues or cell lines when compared with those in tissues of healthy individuals and normal cells." (PMID 22246423, 2012).